ABHD12 (abhydrolase domain containing 12, lysophospholipase)
Diseases named in the same sentence as ABHD12 in open-access papers (continued):
Sharing a sentence is not in itself a finding about the gene and the disease.
dental caries (1 paper, 2025). The decay of a tooth, in which it becomes softened, discolored, and/or porous. "UMAP results showed that ABHD12 was mainly expressed in the carious pulp and was associated with increased dental caries incidence, consistent with the GWAS and cis-eQTL analysis results." (PMID 41444670, 2025). "Further, the G allele of rs2259956 altered the m6A methylation level of ABHD12, which may increase dental caries susceptibility by affecting nearby m6A modification sites." (PMID 41444670, 2025). "The upregulation of ABHD12 could alter the function of DCs and the process of oxidative phosphorylation, shift dental pulp immunity toward a pro-inflammatory state, and thereby increase the risk of dental caries." (PMID 41444670, 2025). "In this study, ABHD12 was identified and characterized as a novel m6A-regulated target in dental caries." (PMID 41444670, 2025). "Notably, ABHD12, which is mainly expressed in carious pulp, validates that upregulation of ABHD12 would increase the incidence of developing dental caries." (PMID 41444670, 2025).
liver cancer (1 paper, 2024). An epithelial or non-epithelial malignant neoplasm that arises from the liver. "ABHD12 promotes tumor growth and sorafenib resistance in liver cancer, with co-delivery of sorafenib and ABHD12 inhibitor enhancing therapeutic efficacy." (PMID 39315094, 2024).
melanoma (1 paper, 2025). A malignant, usually aggressive tumor composed of atypical, neoplastic melanocytes. "Unexpectedly, the most frequently expressed 2-AG-hydrolyzing enzymes MAGL, ABHD6, and ABHD12 were absent in melanoma and skin tissues." (PMID 39934865, 2025).
progressive ataxia (1 paper, 2025). "Zebrafish with ABHD12 gene dysfunction exhibited progressive ataxia, motor skill disorder, retinal dysfunction, cataract, and decreased hair cells in the inner ear." (PMID 39910854, 2025).
neurodegenerative disease (8 papers, 2012 to 2025). A disorder of the central nervous system characterized by gradual and progressive loss of neural tissue and neurologic function. "Establishing the causative agent for neurodegeneration in patients with ABHD12 variants is pivotal for the development of treatment modalities for this neurodegenerative disease." (PMID 34573385, 2021). "It was recently reported that mutations in the ABHD12 gene that are predicted to compromise catalytic activity severely, are causally linked to a neurodegenerative disease called PHARC (polyneuropathy, hearing loss, ataxia, retinitis pigmentosa, and cataract)." (PMID 21418147, 2012). "Mutations in ABHD12 gene are causally linked to a neurodegenerative disease called PHARC." (PMID 21418147, 2012). "The postulated causal link between ABHD12 mutations and the neurodegenerative disease PHARC should stimulate further research that will clarify whether ABHD12 is a molecular component of the eCB system." (PMID 21418147, 2012). "Indeed, other studies suggest that mutations in ABHD12 may contribute to neurodegenerative diseases due to alterations in eCB metabolism." (PMID 34335305, 2021).
neurological disorder (7 papers, 2016 to 2025). "In mammals, the lipase ABHD12, mutations of which cause the human neurological disorder PHARC, metabolizes immunomodulatory lyso‐PS and pro‐apoptotic oxidized PS lipids." (PMID 34727579, 2021). "The integral membrane serine hydrolase enzyme ABHD12 is expressed highly in the central nervous and immune system, and mutations to this enzyme in humans result in the neurological disorder PHARC." (PMID 30237167, 2018). "ABHD12 plays additional important roles in lipid metabolism in the brain, where the enzyme serves as a major lyso-PS hydrolase that is part of an immunomodulatory pathway linked to the human neurological disease PHARC." (PMID 26779719, 2016). "Interestingly, in mammals, both these signalling lipids are physiologically regulated by the lipase ABHD12, mutations of which cause the human neurological disorder PHARC." (PMID 34727579, 2021).
cancer (3 papers, 2021 to 2023). A tumor composed of atypical neoplastic, often pleomorphic cells that invade other tissues. "Firstly, we evaluated the expression levels of endogenous MAGL, ABHD6, and ABHD12 in the cancer cells by western blot analysis." (PMID 36105202, 2022). "Therefore, even though we still do not know how CPT1C regulates ABHD12 activity, we cannot rule out a role for the CPT1C-ABHD12 complex in cancer cell progression." (PMID 36693836, 2023).
tumor (3 papers, 2024 to 2025). "Indeed, chronic stress in tumour‐bearing mice led to the upregulation of 3 proteins (Cpt1c, Faah, Abhd12) involved in lipid metabolism." (PMID 40172096, 2025).
ABHD12 also shares sentences with these, for which no sentence is quoted: polyneuropathy (27 papers); retinitis pigmentosa (27); cerebellar ataxia (3); Blindness (2); demyelinating polyneuropathy (2); Refsum disease (2); Usher syndrome type 3 (2); auditory neuropathy (1); autosomal recessive disease (1); Bardet-Biedl syndrome (1); ciliopathy (1); cognitive decline (1); Dystonia (1); Hearing impairment (1); hypomyelinating leukodystrophy (1); infection (1); infectious disease (1); Kohlschutter’s syndrome (1); lens disorder (1); Nystagmus (1); peripheral neuropathy (1); Retinal dystrophy (1); retinopathy (1); Spasticity (1); spinocerebellar ataxia type 10 (1).